ANGPT2 (angiopoietin 2)
Diseases named in the same sentence as ANGPT2 in open-access papers (continued):
Sharing a sentence is not in itself a finding about the gene and the disease.
pancreatic ductal adenocarcinoma (2 papers, 2022 to 2024). An infiltrating adenocarcinoma that arises from the epithelial cells of the pancreas. "Ang-2 (angiopoietin 2) contributes to pancreatic ductal adenocarcinoma (PDAC) metastasis by promoting lymphatic vascularization and enhancing tumor cell interactions with endothelial cells." (PMID 39195316, 2024).
renal dysfunction (2 papers, 2016 to 2025). "Notably, patients with CKD or renal dysfunction display changes in corresponding genes, such as a loss of the endothelial marker CDH5, an increase in ANGPT2 and PDGFB, and a reduction in ANGPT1." (PMID 40952790, 2025).
small cell lung carcinoma (2 papers, 2024 to 2025). Small cell lung cancer (SCLC) is a highly aggressive malignant neoplasm, accounting for 10-15% of lung cancer cases, characterized byrapid growth, and early metastasis. "Inhibition of the integrin β-1 signaling pathway reliant on angiopoietin-2 significantly reduces the invasion and spread of small cell lung carcinoma." (PMID 40061897, 2025).
systemic sclerosis (2 papers, 2020 to 2024). A chronic disorder, possibly autoimmune, marked by excessive production of collagen which results in hardening and thickening of body tissues. "ANGPT2 promotes inflammatory activation of monocytes in patients with systemic sclerosis." (PMID 38808888, 2024).
Acidosis (1 paper, 2022). Abnormal acid accumulation or depletion of base. "While angiopoietin 2 (Angpt-2) and P-selectin were associated with TFF3, I-FABP was correlated with soluble Fms-related receptor tyrosine kinase 1 (sFlt-1) as well as soluble vascular cell adhesion molecule 1 (sVCAM-1) in children with acidosis." (PMID 36069443, 2022).
adenomyosis (1 paper, 2025). The growth of endometrial tissue inside the muscular wall of the uterine corpus. "Our study demonstrates that LNG-IUS treatment is associated with lower protein expression of VEGF, ANGPT-1, and ANGPT-2 in adenomyosis, with levels approaching those observed in normal controls." (PMID 41464535, 2025). "The LNG-IUS attenuates ANGPT-1, ANGPT-2, and VEGF expression at both the protein and transcript levels, suggesting that modulation of angiogenic pathways may contribute to its therapeutic benefit in abnormal uterine bleeding associated with adenomyosis." (PMID 41464535, 2025). "Although TIE-2 receptor expression itself remains stable during the menstrual cycle, our observation of increased ANGPT-1 and ANGPT-2 levels in adenomyosis patients indicates that altered ligand activity, rather than receptor availability, may contribute to aberrant angiogenesis." (PMID 41464535, 2025). "We compared vascular endothelial growth factor (VEGF), angiopoietin-1 (ANGPT-1), and angiopoietin-2 (ANGPT-2) expression in eutopic and ectopic endometria from patients with adenomyosis and evaluated whether the levonorgestrel intrauterine system (LNG-IUS) modulates these angiogenic markers." (PMID 41464535, 2025). "In adenomyosis patients using the LNG-IUS, these expression levels were lower and approached those of the control group, ANGPT1, ANGPT2, and VEGFA mRNA in eutopic endometria showed concordant downregulation." (PMID 41464535, 2025). "The protein expression of ANGPT-1, ANGPT-2, and VEGF was significantly elevated in both eutopic and ectopic endometria of patients with adenomyosis compared with normal controls." (PMID 41464535, 2025). "The objective of this study was therefore to evaluate the expression of VEGF, ANGPT-1, and ANGPT-2 in eutopic and ectopic endometria from patients with adenomyosis—with and without LNG-IUS insertion—compared with normal controls." (PMID 41464535, 2025).
Airway obstruction (1 paper, 2016). Obstruction of conducting airways of the lung. "Angiopoietin-2 correlated also with airway obstruction reversibility defined as percentage of increase in FEV1 after inhalation of 2.5 mg of salbutamol (R = 0.22; p < 0.05)." (PMID 26937244, 2016).
aneurysm (1 paper, 2025). Bulging or ballooning in an area of an artery secondary to arterial wall weakening. "Studies indicate that signaling pathways related to angiogenesis are abnormally enhanced in CA ECs, and specific genes such as Angiopoietin‐2 (ANGPT2) participate in aneurysm formation." (PMID 40384564, 2025).
angioedema (1 paper, 2024). Swelling involving the deep dermis, subcutaneous, or submucosal tissues, representing localized edema. "In addition, the ANGPT2/ANGPT1 ratio (an index of vascular permeability) was decreased during angioedema attacks." (PMID 38829492, 2024).
Aortic dissection (1 paper, 2021). Aortic dissection refers to a tear in the intimal layer of the aorta causing a separation between the intima and the medial layers of the aorta. "Therefore, whether aorta with high expression of ANGPT2 increases the risk of aortic dissection needs clinical perspective studies or animal experiments to confirm." (PMID 35004874, 2021).
arteriovenous malformations (1 paper, 2023). "Other mice studies also suggested that Angpt2 was an important mediator of arteriovenous malformations through the control of TGFβ signaling." (PMID 37533068, 2023).
Atrophy (1 paper, 2015). Any weakening or degeneration, especially through lack of use. "The angiogenic factors Vegfa, Fgf1 and Angiopoietin 2 were significantly up-regulated at day 7 in the atrophy group." (PMID 25910190, 2015). "In all calluses of the atrophy group, the ANGPT2 signal was more intense in cells of the callus periphery compared to the other two groups." (PMID 25910190, 2015).
bacterial pneumonia (1 paper, 2023). Acute infection of the lung parenchyma caused by bacteria (e.g., Streptococcus pneumoniae, Haemophilus influenzae, Chlamydia pneumoniae, Mycoplasma pneumoniae, and Legionella pneumophila). "We measured mature miR-1 and ANGPT2 levels in the serum samples from 119 patients who were admitted with bacterial pneumonia." (PMID 37737266, 2023).
benign prostatic hyperplasia (1 paper, 2022). A non-cancerous nodular enlargement of the prostate gland. "In benign prostatic hyperplasia (BPH) and prostate cancer, Dkk-3 increases ANGPT2 expression, a destabilizing factor that leads to the formation of vessel sprouting in the tumor microenvironment." (PMID 36497305, 2022).
bone sarcoma (1 paper, 2014). A sarcoma that arises from the bone. "We did observe that increased expression of ANGPT2 and CDC25A was maintained throughout culture passages; however, these genes are not correlated with bone sarcoma etiology." (PMID 24716831, 2014). "ANGPT2 and CDC25A maintain higher expression levels during in vitro culture in MSC-SAR compared to MSC-CTRL, but expression of these genes has not been correlated with bone sarcoma etiology." (PMID 24716831, 2014).
brain injury (1 paper, 2022). Acute and chronic (see also brain INJURIES, CHRONIC) injuries to the brain, including the cerebral hemispheres, CEREBELLUM, and brain STEM. "Plasma sST2 also correlated with an elevated angiopoietin-2/angiopoietin-1 ratio, which has been seen in and is thought to contribute to sequelae from traumatic brain injury." (PMID 35800259, 2022).
breast adenocarcinoma (1 paper, 2019). "Consistently, in vitro treatments by folic acid in MCF-7 which is well-known as ER + /PR + breast adenocarcinoma cells, represented significant increased in ANGPT2/VEGF levels." (PMID 31619709, 2019).
bronchiectasis (1 paper, 2022). Segmental, irreversible dilation of the bronchial tree resulting in the accumulation of secretions which leads to obstruction. "We assessed the association of serum fibrinogen, adiponectin, and angiopoietin-2 levels with the severity and exacerbation of bronchiectasis." (PMID 35887712, 2022). "This study investigated the clinical significance of serum fibrinogen, adiponectin, and angiopoietin-2 as biomarkers of bronchiectasis." (PMID 35887712, 2022). "As a component of the authors’ biomarker study in bronchiectasis, serum levels of fibrinogen, adiponectin, and angiopoietin-2 were tested to determine their role as significant biomarkers." (PMID 35887712, 2022). "We evaluated the potential of fibrinogen, adiponectin, and angiopoietin-2 as meaningful biomarkers of bronchiectasis in this study." (PMID 35887712, 2022). "Correlations of adiponectin and angiopoietin-2 levels with BSI or FACED score in patients with bronchiectasis were not significant." (PMID 35887712, 2022). "In conclusion, serum fibrinogen level, but not adiponectin or angiopoietin-2, may represent a potential biomarker of disease severity and exacerbation of bronchiectasis." (PMID 35887712, 2022).
cerebral cavernous malformation (1 paper, 2021). A disorder characterized by malformations in the structure of the capillaries in the brain. "Angiopoietin-2 is dysregulated in mouse cerebral cavernous malformation (CCM), but its inhibition rescues arteriovenous malformation (AVM) in a hereditary haemorrhagic telangiectasia (HHT) mouse model." (PMID 33688979, 2021).
cerebrovascular diseases (1 paper, 2025). "In particular, levels of Angiopoietin-2 (Ang2) are dramatically elevated in cardiovascular and cerebrovascular diseases, such as coronary heart disease and stroke, with disease severity positively correlated with increased Ang2 levels." (PMID 40432894, 2025).
choroidal neovascularization (1 paper, 2025). An eye disorder described by the growth of new blood vessels that originate from the choroid through a break in the Bruch membrane into the sub–retinal pigment epithelium (sub-RPE) or subretinal space. "The RPE-tropic AAV vector delivered a dual-acting antibody against vascular endothelial growth factor (VEGF) and angiopoietin-2 (ANG-2), exhibiting strong therapeutic efficacy and tolerability in both rodent and nonhuman primate choroidal neovascularization models." (PMID 40443830, 2025).
Chylothorax (1 paper, 2019). The presence of chyle in the thoracic cavity. "Deletion of Angpt2 results in a strain-specific postnatal lethality in mice due to severe chylothorax." (PMID 31582413, 2019).
co-infection (1 paper, 2016). "In Malawian children with severe bacterial infection, a greater increase in plasma angiopoietin-2, an angiogenic peptide that increases endothelial activation and vascular permeability, was observed in patients with HIV co-infection." (PMID 27719675, 2016).
complication (1 paper, 2021). Any disease or disorder that occurs during the course of, or because of, another disease, treatment, or procedure. "When comparing patients with T1DM with or without vascular complications, the highest ANGPT-2 levels were observed in those with complications." (PMID 34762787, 2021).
Crohn disease (1 paper, 2025). A gastrointestinal disorder characterized by chronic inflammation involving all layers of the intestinal wall, noncaseating granulomas affecting the intestinal wall and regional lymph nodes, and transmural fibrosis. "Furthermore, thalidomide has been shown to reduce the protein expression of angiopoietin-2 (ANGPT-2) and VEGF as well as to decrease mRNA expression of ANGPT-2 in patients with Crohn’s disease, a condition characterized by elevated levels of these proteins." (PMID 40091828, 2025).
dialysis (1 paper, 2024). "Our objective was to examine the factors associated with the serum angiopoietin-2/angiopoietin-1 (Angpt-2/Angpt-1) ratio in peritoneal dialysis (PD) patients and to investigate the association between Angpt-2/Angpt-1 ratio and cardiovascular and all-cause mortality." (PMID 39082686, 2024).
Encephalopathy (1 paper, 2016). Encephalopathy is a term that means brain disease, damage, or malfunction. "More specifically, angiopoietin 2 was reported to be significantly increased in patients with encephalopathy related to HUS but not in patients without encephalopathy." (PMID 27802295, 2016).
endometrioid endometrial carcinoma (1 paper, 2003). "We investigated the presence of transcripts for VEGF-A, VEGF-B, VEGF-C, VEGF-D, Angiopoietin-1 and Angiopoietin-2 in benign endometrium, atypical complex hyperplasia (ACH) and endometrioid endometrial carcinoma using in situ hybridisation." (PMID 12942123, 2003).
eosinophilia (1 paper, 2016). "However, no direct correlation of the Angiopoietin-2 levels with blood eosinophilia, serum ECP or total IgE levels was found." (PMID 26937244, 2016).
Erythema (1 paper, 2025). Redness of the skin, caused by hyperemia of the capillaries in the lower layers of the skin. "For example, UV irradiation has been shown to induce the release of Angiopoietin 2 from dermal vascular endothelial cells as a mechanism of UV-induced erythema characterized by inflammatory and angiogenic response, supporting the potential role of UV in the pathogenesis of rosacea." (PMID 41562711, 2025).
gallbladder cancer (1 paper, 2025). "Using a luciferase activity assay, Diao et coworkers identified that ANGPT2 is a potential target gene of miR−135a−5p in gallbladder cancer cells." (PMID 40115011, 2025).
gastric tumors (1 paper, 2020). "Chen Z's research indicated that DARPP‐32 can further regulate the angiogenic effect of ANGPT2 by inducing STAT3 phosphorylation in gastric tumors." (PMID 33090721, 2020).
gastritis (1 paper, 2023). Inflammation of the stomach. "Therefore, we used a mouse model of H. pylori-induced gastritis to explore the kinetics of the expression of Angpt1, Angpt2, Tnf-α and Vegf-A in vivo." (PMID 36874142, 2023).
gestational diabetes (1 paper, 2021). Carbohydrate intolerance first diagnosed during pregnancy. "Moreover, proof-of-concept studies found that secreted placental proteins (sFLT1/MIF and ANGPT2/MIF ratios) were increased in women prior to diagnosis of gestational diabetes." (PMID 34103657, 2021).
glomerular diseases (1 paper, 2020). "In physiology, Angpt1 is expressed by glomerular cells and pericytes, while Angpt2 expression is absent; increased levels of Angpt2 have been observed in glomerular diseases and appear to be correlated to adverse outcomes." (PMID 33067928, 2020).
glomerulosclerosis (1 paper, 2026). A hardening of the kidney glomerulus caused by scarring of the blood vessels. "We assessed microthrombi, tubular necrosis, glomerulosclerosis, fibrosis, and expression of angiopoietin-2 and thrombomodulin." (PMID 41620635, 2026).
head and neck squamous cell carcinoma (1 paper, 2021). A squamous cell carcinoma that arises from any of the following anatomic sites: lip and oral cavity, nasal cavity, paranasal sinuses, pharynx, larynx, and salivary glands. "The genotypes ANGPT2 (rs3739391) GA/AA, ANGPT2 (rs3020221) CC, TEK (rs639225) GA/AA, and VEGF (rs2010963) CC was related to decreased OS in patients with head and neck squamous cell carcinoma treated with the combination therapy." (PMID 34209679, 2021).
heart malformations (1 paper, 2023). "Thus, it is unclear whether congenital heart malformations are a feature of the homozygous ANGPT2 phenotype." (PMID 34876502, 2023).
hydrops fetalis (1 paper, 2023). Hydrops fetalis is a severe and challenging fetal condition usually defined as the excessive accumulation of fetal fluid within the fetal extravascular compartments and body cavities that manifests as edema, pleural and pericardial effusion and ascites. "Taken together with earlier reports in humans and the murine model, we nonetheless believe that lymphatic dysplasia is the likely underlying cause of ANGPT2-related fetal hydrops." (PMID 34876502, 2023). "Whole exome sequencing in four fetuses with hydrops fetalis revealed that they were homozygous for the angiopoietin-2 (ANGPT2) variant Chr8 (GRCh37/Hg19): 6385085T>C, NM_001147.2:c.557A>G." (PMID 34876502, 2023). "In conclusion, we report the first family with severe, early-onset hydrops fetalis caused by a homozygous LOF variant in ANGPT2." (PMID 34876502, 2023). "In the homozygous affected fetuses, there was likely a complete absence of ANGPT2 with resultant impaired lymphatic development and severe, lethal hydrops fetalis." (PMID 34876502, 2023).
ischemic cardiomyopathy (1 paper, 2023). Ischemic cardiomyopathy is a cardiomyopathy in which a weakness in the muscle of the heart due to inadequate oxygen delivery to the myocardium with coronary artery disease being the most common cause. "There are two emerging biomarkers for ischemic cardiomyopathy: angiopoietin-2 and thrombospondin-2, that are now used in addition to BNP and cardiac troponin." (PMID 37210547, 2023).
ischemic disease (1 paper, 2022). Lack of blood supply to an area of the body, resulting in impairment of tissue oxygenation. "In ischemic diseases such as DR, the upregulation of Angpt2 inactivates Tie2, leading to vascular leakage, pericyte loss, and inflammation." (PMID 36533134, 2022).
lentivirus infection (1 paper, 2020). Virus diseases caused by the Lentivirus genus. "We used two HCC cell lines (Hep3B and MHCC97H) to overexpress ANGPT2 by lentivirus infection or knockdown ANGPT2 by the CRISPR/Cas system." (PMID 32183816, 2020).
limb ischemia (1 paper, 2020). A ischemia that involves the limb. "For example, the upregulation of Angpt2 in CS mice may point to altered blood vessel growth in the ischemic brain as angiopoietin-2 has been shown to impair revascularization after limb ischemia." (PMID 31758402, 2020).
lymphatic disorders (1 paper, 2024). "Furthermore, whether compound genetic variants in genes in the PIEZO1/ANGPT2/TIE/FOXO1 pathway predispose to lymphatic disorders in humans was not explored here and remains an interesting path for future investigation." (PMID 38747287, 2024).
mastocytosis (1 paper, 2021). A clonal myeloproliferative neoplasm characterized by the proliferation and accumulation of neoplastic mast cells in one or multiple organs or organ systems. "ANGPT2 levels, like tryptase, were higher in patients with advanced mastocytosis compared to indolent variants." (PMID 33687603, 2021). "The aim of this paper was to evaluate the serum concentrations of VEGF-A, VEGF-C, VEGF-D, ANGPT1 and ANGPT2 in patients with different variants of mastocytosis and the expression of angiogenic and lymphangiogenic factors in human MC lines with or without D816V mutation." (PMID 33687603, 2021). "Serum concentrations of VEGF-A, VEGF-C, VEGF-D, ANGPT1 and ANGPT2 were determined in 64 mastocytosis patients and 64 healthy controls." (PMID 33687603, 2021). "Serum concentrations of VEGF-A, VEGF-C, ANGPT1 and ANGPT2 are increased in patients with mastocytosis compared to healthy controls." (PMID 33687603, 2021). "ANGPT2, which is released mainly by endothelial cells, and ANGPT1/ANGPT2 ratio, an index of vascular permeability, are increased only in advanced mastocytosis." (PMID 33687603, 2021). "VEGF-A, ANGPT1, ANGPT2 and VEGF-C concentrations were higher in mastocytosis patients compared to controls." (PMID 33687603, 2021). "It is possible to speculate that the increase in circulating ANGPT1 in all patients with mastocytosis might represent a protective factor in counterbalancing the vasopermeability effect of VEGF-A and ANGPT2." (PMID 33687603, 2021). "A triplex experimental analysis was used to verify whether enhanced levels of VEGF-A, ANGPT1, ANGPT2 and VEGF-C were correlated with mastocytosis severity." (PMID 33687603, 2021). "Interestingly, both ANGPT2, which increases vascular permeability, and its antagonist ANGPT1 were increased in mastocytosis patients compared to HC [ANGPT1: (1,538 ± 2,136) vs (39.93 ± 45.60 pg/mL)] [ANGPT2: (1,492 ± 976) vs (1,085 ± 607) pg/mL]." (PMID 33687603, 2021). "In fact, circulating levels of VEGF-A, ANGPT2 and VEGF-C are increased in symptomatic, but not asymptomatic mastocytosis patients." (PMID 33687603, 2021).
meningioma (1 paper, 2018). A generally slow growing tumor attached to the dura mater. "Six of these genes were usually underexpressed (RUNDC3B, ANGPT2, PHLDA2, CAV2, EDNRA, and SCG2) in non-aggressive/non-recurrent tumors and overexpressed in more aggressive/recurrent meningiomas." (PMID 29662628, 2018).